CD24 (CD24 molecule)
Diseases named in the same sentence as CD24 in open-access papers (continued):
Sharing a sentence is not in itself a finding about the gene and the disease.
breast cancer (continued). "Breast cancers with high CD44 and low CD24 have been associated with the triple negative subtype (negative for estrogen receptor (ER), progesterone receptor (PR), and HER2 receptor) and with poorer prognosis." (PMID 29600163, 2018). "We demonstrate that SMAD5 expression is required to induce a CD44+/CD24-/ALDH1+ breast cancer stem cell-like phenotype, suggesting that the Aurora-A/SMAD5 axis promotes chemoresistance through activation of stemness signalling in breast cancer." (PMID 29207686, 2017). "Tumor-initiating cells (TICs) are cancer cells endowed with self-renewal, multi-lineage differentiation, increased chemo-resistance, and in breast cancers the CD44+/CD24-/ALDH1+ phenotype." (PMID 28052035, 2017). "This study aimed to analyze the effect of extracellular alkalinization on metabolism and survival of human CD24-/CD44+ breast cancer stem cells (BCSCs)." (PMID 28746471, 2017). "It has been reported that breast cancer cells with the CD44+CD24– phenotype and stem-cell–like features are highly resistant to cancer therapies." (PMID 28240233, 2017). "Our studies using antisense tools to up-regulate and down-regulate CD24 in breast cancer cells suggest a relationship between CD24 expression and biomarkers of autophagy in vitro." (PMID 28418843, 2017). "Our data showed that ACEA has an inhibitory effect on CD44+/CD24-breast cancer stem cell and their parental cell invasion but AM251 increases invasiveness." (PMID 29552056, 2017). "These stem-like breast cancer cells can be isolated using specific markers including a CD44+CD24- phenotype and/or high aldehyde dehydrogenase activity (ALDHhi)." (PMID 28498874, 2017). "Other cell surface markers, like CD49f and CD133, can, when combined with CD44+ and CD24−, be used to identify BCSCs in different breast cancer subtypes." (PMID 29258583, 2017). "In recent years, CD24 overexpression has been correlated with shorter patient survival in breast cancer, ovarian cancer, non-small cell lung carcinomas, prostate tumors, colorectal cancer, and in esophageal squamous cell carcinoma." (PMID 28611669, 2017). "Our recent study showed decrease in CD24 and EpCAM expression in mammary cancer cells in rats after oregano treatment." (PMID 28524540, 2017). "In the present study, we evaluated the effect of CB1 agonist and antagonist on proliferation and invasion potential of (CD44+/CD24-/low/ESA+) human breast cancer stem cells which were derived from MDA-MB-231 and their parental cells." (PMID 29552056, 2017). "It has also been reported that highly tumorigenic breast cancer stem cells (CD44+CD24-/low) are generated through activation of the Ras pathway in EMT, providing a direct link between EMT and cancer stem cells." (PMID 28114432, 2017). "In breast cancer, CD24-expressing cancer cells can disseminate more readily through their capacity to form thrombi with platelets or bind to endothelial cells in the bloodstream." (PMID 28611669, 2017). "IL-6 is a direct regulator of breast CSC self-renewal and IL-6/JAK2/STAT3 pathway is more active in CD44(+)CD24(-/low) breast cancer cells compared with other tumor cell types and its inhibition blocks the growth of xenografts." (PMID 28270211, 2017). "Evidence of the breast CSCs resistance is supported by a study in which tumor biopsies taken from patients with breast cancer during the 12-week chemotherapy treatment conducted increased CSC markers (CD44+/CD24-/low and MFSE)." (PMID 28245823, 2017). "Overall, our findings indicate the association of intratumor morphological heterogeneity in breast cancer with the epithelial-mesenchymal transition and CD44+CD24- stemness and the appeal of this heterogeneity as a model for the study of cancer invasion." (PMID 28977854, 2017). "As previously discussed, “stem-like” ALDHhiCD44+ CD24- breast cancer cells show enhanced metastasis to multiple different organs, including bone." (PMID 28498874, 2017).
breast cancer (continued). "The mechanism underlying the different expression of CD44/CD24 and ALDH1 in breast cancer has yet to be found." (PMID 29062075, 2017). "In another, c/m-CD24 expression was shown to be specific a marker for tamoxifen-resistant breast cancer cases." (PMID 28052035, 2017). "Both putative breast cancer stem cell subpopulations expressing the ALDH1 or the CD44+CD24-/low phenotype, showed similar sphere formation efficiency." (PMID 28423035, 2017). "Breast cancer cells that undergo EMT acquire a basal-like CD44+/CD24- stemness phenotype characterized by a greater capacity for tumor self-renewal and early onset of distant metastasis." (PMID 29207686, 2017). "CD24 overexpression has also been related to shorter distant metastasis-free survival in breast cancer patients." (PMID 28929082, 2017). "Although CD44 and CD24 are well-established markers of breast cancer stemness, they are not universal surface markers for the definitive characterization of a breast cancer stem-like phenotype." (PMID 29207686, 2017). "The MDA-MB-231 and HS-578T cell lines possess the highest number of CD44+CD24−/low cells while MCF-7 and T-47D luminal as well as MDA-MB-468 basal-like breast cancer cell line are characterized by very low number of CD44+CD24−/low cells." (PMID 27845900, 2017). "A third study showed that CD44+CD24-/low cells were concentrated in breast cancers invasive protrusions." (PMID 28052035, 2017). "CD24 cross-linking antibody induced apoptosis in human and mouse m-CD24-expressing B cells, reduced growth and migration in human m-CD24-expressing colorectal and breast cancer cell lines, and now in IRISOE/TNBC/TICs (this study)." (PMID 28052035, 2017). "The increase in CD24 was consistent with the observation that estrogen mediated downregulation of CD24 in breast cancer cells." (PMID 28929082, 2017). "Marotta and the colleagues reported that the JAK2/STAT3 signaling pathway was required for growth of CD44+CD24− stem cell-like breast cancer cells." (PMID 28591704, 2017). "We detected a significant reduction in the percentage of the CD24+CD90+ cancer stem cell population in PyVT/KO mammary tumors compared to PyVT tumors." (PMID 29051494, 2017). "According to classical notions the differentiation of tumor cells during the breast cancer development is accompanied by the reduced expression of CD-44 receptor with its gradual disappearance and appearance of the cells expressing the CD24 marker." (PMID 28622715, 2017). "Fillmore C. and Kuperwasser C. supposed that CD24+ population was mainly characterized by less differentiated basal type of breast cancer, and CD44+ cells caused the development of luminal form of breast cancer, being more differentiated type of tumor." (PMID 28622715, 2017). "CD24 is a small, heavily glycosylated cell surface receptor frequently overexpressed in a wide range of carcinomas, including breast carcinomas." (PMID 28052035, 2017). "Lower expression of CD24, CD44, ALDH1 and EpCAM is linked with better prognosis of breast carcinoma in patients." (PMID 28524540, 2017). "Cell surface markers such as CD44+/CD24-/low have been used to separate mammary stem/progenitor cells from differentiated breast cancer cells." (PMID 27529753, 2016). "To test the feasibility of our results in CD24+ human breast cancer cells, we downregulated IGF1R in the MCF7 cells and identified a marked reduction in SLPI levels." (PMID 27179633, 2016). "Taken together, this suggests a potential role for HIF-1 regulation in CD24 overexpression in breast cancer." (PMID 27706047, 2016). "Similar work demonstrated the chemotherapy resistant nature of the CD24-/CD44+ enriched population of breast cancer cells." (PMID 27028405, 2016). "The pairing of CD44 and CD24 was first employed to select for TICs in solid tumors, leading to observations that in breast cancer the CD44High/CD24Neg/Low sub-population has enriched TIC activity." (PMID 27001172, 2016).
breast cancer (continued). "In this study we demonstrate that CD24+CD90+CD45− cancer cells of the MMTV- PyMT breast cancer model possess high tumorigenicity in clonogenic in vitro assays as well as in vivo upon transfer of only 100 cells into the mammary fat pad of immunodeficient mice." (PMID 27542270, 2016). "In conclusion, high extra- and intracellular proteolytic activity as well as high expression of transmembrane Mmp14 are hallmarks of CD24+CD90+ TICs in the MMTV-PyMT breast cancer model." (PMID 27542270, 2016). "Breast cancer stem cells, identified as a CD24-/CD44+ enriched population growing as spheres, showed increased resistance to irradiation when compared to a non-enriched, monolayer culture." (PMID 27028405, 2016). "In breast cancer cells, CD24 is suggested to increase HER2 expression by transcriptional machineries via NF-κB signaling." (PMID 26830684, 2016). "Breast cancer cells that express less CD24 and more CD44 are more de-differentiated and more stem cell-like." (PMID 26832928, 2016). "Our results demonstrated that miR-199a-5p indeed inhibited the breast cancer cell stemness by decreasing the CD24-/CD44+ population and ALDH activity." (PMID 27842518, 2016). "When different digestive agents were compared with regards to their effect on the presence of CD44 and CD24 surface markers in a breast cancer cell line, differences were observed." (PMID 27766946, 2016). "Basal-B cells express high CD44 and CDK4, along with high levels of the mesenchymal marker vimentin, while basal-A or luminal-like breast cancer cells display higher CD24 level with a high expression level of the epithelial marker E-cadherin." (PMID 27759034, 2016). "In the MMTV-Wnt1 model for breast cancer TICs can be isolated based on the cell surface markers CD24+ and CD90+ (Thy1) and the exclusion of CD45 positive leukocytes." (PMID 27542270, 2016). "A recent study using breast cancer biopsy tissues showed that chemotherapy led to an increased percentage of CD44+/CD24+ cells, consistent with increased clone formation ability." (PMID 27323403, 2016). "The CD44+/CD24-/ESA+ subpopulation has been identified as being significantly enriched in the breast cancer stem cell population." (PMID 26821678, 2016). "CD24 expression serves as a marker for poor outcome in breast cancer patients, and we have recently demonstrated that CD24+ Mvt1 cells are highly tumorigenic compared with their CD24- counterparts." (PMID 27179633, 2016). "The expression of CD44+/CD24-/low has been extensively used as markers for breast cancer stem cells." (PMID 27416801, 2016). "The expression level of CDK4, CD44, and CD24 was analyzed in 51 breast cancer cell lines containing mesenchymal-like (basal-B) and epithelial-like (basal-A and luminal) phenotypes." (PMID 27759034, 2016). "The first TICs in human breast cancers were identified based on the cell surface makers CD44+CD24-/low." (PMID 27542270, 2016). "Stemness-enriched breast cancer cells have a CD44+/CD24− phenotype and higher NF-κB activity than CD44−/CD24+ breast cancer cells." (PMID 28116318, 2016). "Western blotting showed that stem cell markers CD44 increased and CD24 decreased in the breast cancer cells with conditioned medium treatment, and the ratio of CD44+CD24− breast cancer cells became more than the control." (PMID 27325313, 2016). "Our data show that in luminal-like MMTV-PyMT and in metaplastic Apc1572T/+ tumors that represent a model for a subtype of human triple negative basal-like breast cancers, CD24 can be upregulated during early tumorigenesis." (PMID 26978528, 2016).
breast cancer (continued). "In breast cancer cell lines, CD24 expression reduces stromal cell-derived factor-1-mediated migration and signalling via CXCR4, suppressing their metastatic potential, whilst CD24−/low cells have conversely been shown to increase metastatic potential." (PMID 27189371, 2016). "This indicates stemness and potential tumorigenicity for CD24+CD90+ cells derived from MMTV-PyMT breast cancers." (PMID 27542270, 2016). "Recently, based on CD24 cell surface expression we were able to distinguish, sort and maintain two distinct subpopulations of the metastatic mammary carcinoma cell line, Mvt1 that overexpresses the c-Myc and VEGF oncogenes." (PMID 27179633, 2016). "Similar results were observed in the subpopulation of BrCSCs obtained by sorting the bulk population for the expression of the breast cancer stem cell markers CD49f and CD24." (PMID 25537513, 2015). "Our results demonstrated that DSF treatment suppressed the expression of breast CSCs markers (ALDH+, CD44+/CD24−), and abolished the sphere-forming ability in breast cancer cells at a concentration of 10–15 μM." (PMID 26517513, 2015). "In this study, we have discovered that RP215-recognized IgG was overexpressed CSC-like cells such as CD44+/CD24−/low of breast cancer cells, and the p63+ adult stem/progenitor cells of many stratified epithelium." (PMID 26472025, 2015). "For example, CD24 marks normal mammary stem cells but in combination with the other cell surface markers, CD24-negative breast cancer cells are those with the greatest tumour-initiating potential." (PMID 25866586, 2015). "In stark contrast, forced expression of CD24 in breast cancer cells that have low CD24 expression (CD24−) leads to decreased cell proliferation." (PMID 26301220, 2015). "CD24 immunostaining was predominantly localised in the membrane and/or cytoplasm of breast cancer cells." (PMID 26444008, 2015). "Previous studies reported that positive CD24 expression is an unfavourable prognostic factor in breast cancer." (PMID 26444008, 2015). "CD34+ was used for leukemia-initiating cells, and CD44+CD24− or ALDH1+ was used to enrich breast cancer-initiating cells." (PMID 26376676, 2015). "In our recent study, we found that CD24+ Mvt-1 form rapidly mammary tumors, moreover, with the tail vein assay, our results demonstrated metastatic phenotype of these CD24+ cells." (PMID 26484297, 2015). "In order to find heterogeneity and hierarchal organization in the mammary carcinoma Mvt1 cell line, we characterized the cell surface expression of CD29, CD61/β3, CD24 and CD49f, common markers for isolation of mammary cancer stem cells." (PMID 26040280, 2015). "The mammosphere cells were separated and characterized for surface expression of CD44 and CD24, which are commonly considered as markers of breast cancer stem cells." (PMID 26315028, 2015). "Previous studies have shown that expression of oncogenic Ras in breast cancer cells generates CD24− cells from CD24+ cells." (PMID 26301220, 2015). "CD24, a known marker for mammary stem and progenitor cells, was proven useful to enrich mammary cancer stem cells." (PMID 26040280, 2015). "As a result, the impact of CD24 expression on patient survival was revealed to be time-dependent in subtypes of breast cancer." (PMID 26444008, 2015). "Based on CD24 expression, we have recently identified two distinct subpopulations in the mammary carcinoma Mvt-1 cell line, which is derived from a primary mammary tumor in MMTV-VEGF/c-myc bi-transgenic female mice." (PMID 26040280, 2015). "CD24 expression was analyzed by immunohistochemistry in 747 breast cancer tissues, and DNA methylation and histone modification status in the promoter region of CD24 were assessed using bisulfite sequencing and chromatin immunoprecipitation assay." (PMID 26444008, 2015). "It has been shown that CD24 expression is dynamically regulated in both CD24+ and CD24− breast cancer cells, with CD24− cells gaining CD24 expression and vice versa." (PMID 26301220, 2015).
breast cancer (continued). "Only CSC-like cells (i.e. CD44+/CD24-) in breast cancer cells respond to TGF-β1 induction for increasing in GSN expression such as to maintain their invasive phenotype." (PMID 26482896, 2015). "It is notable that the influence of CD24 expression on patient survival in the subtypes of breast cancer was time-dependent." (PMID 26444008, 2015). "Breast cancer stem-like cell (BCSC) populations have recently been identified based on the cell membrane markers CD44+/CD24-/ ESA+ cells." (PMID 26338199, 2015). "Accordingly, CD24 in combination with CD44 is currently considered as a marker for cancer stem cells in breast cancer." (PMID 26444008, 2015). "CD24+ cells formed mammary tumors in 83 % of the injection with as few as 100 cells, whereas CD24− cells generated mammary tumors only in 33 % of the cases." (PMID 26040280, 2015). "CD44+/CD24- subpopulation has been found to be enriched with tumor-initiating features, especially in breast cancer cells." (PMID 26185996, 2015). "This is also in line with the increase of CD24 expression in breast cancer cells induced by the HDAC inhibitor TSA." (PMID 26444008, 2015). "CD24+ cells were shown to be highly tumorigenic, with capability to form mammary tumors even when implanted in low numbers." (PMID 26040280, 2015). "In contrast, luminal breast cancer tumors mostly consist of CD44–/CD24+ cells and are thought be more differentiated." (PMID 25993512, 2015). "Review of the literature shows that the role of CD24 in breast cancer and specifically in TNBC has been extensively investigated." (PMID 26504780, 2015). "Earlier studies have shown that breast cancer cells contain stem-cell like cells exhibiting CD44+CD24-/low marker expression and these cells possess more than 50 fold increased tumorigenic capacity when compared to the other cells of tumour mass." (PMID 26355461, 2015). "Here, we report the isolation of subsets of EpCAM-negative breast cancer CTCs containing stem-cell properties (CD44+/CD24−) by multiparametric flow cytometry with a combinatorial uPAR and int β1 expression and their abilities to grow long-term in vitro." (PMID 26631983, 2015). "In contrast, the estrogen receptor (ER) represses CD24 transcription in ER-positive breast cancer cells." (PMID 26301220, 2015). "We also found that CD24 overexpression is an independent unfavourable prognostic factor in breast cancer, especially for the luminal A and TNBC subtypes." (PMID 26444008, 2015). "Under the condition of 2 ng/ml TGF-β1 for 3 days, the population of CD44+/CD24- MDA-MB231 breast cancer cells were increased." (PMID 26482896, 2015). "In contrast, low expression of CD24 leads to cell proliferation and metastasis of breast cancer stem cells (BCSCs)." (PMID 26301220, 2015). "Basal-like breast cancer tumors are known to be abundant in CD44+/CD24– cells and exhibit stem-cell-like characteristics." (PMID 25993512, 2015). "CD44/CD24 expression profiles showed a large variability within breast cancer subtypes especially for TNBCs." (PMID 26504780, 2015). "TMEM176A and TMEM176B, two transmembrane proteins that were recently found to be elevated in breast cancer and other human malignancies were significantly elevated in the CD24+ cells." (PMID 26040280, 2015). "Accordingly, an IL-6/STAT3 pathway was preferentially active in CD44+/CD24- breast cancer stem cells and PTEN was shown to negatively regulate TIC manteinance through STAT3-dependent signalling." (PMID 26486080, 2015). "CD24 expression was a poor prognostic marker in HR-positive breast cancer, and CD44 expression was a good prognostic marker in the HR-negative group." (PMID 25429827, 2015). "CD24 expression can be downregulated by activation of the estrogen receptor in human breast cancer cells." (PMID 26536476, 2015). "The breast cancer spheroids generated by us under specific culture conditions showed altered levels of the breast CSC markers CD44+CD24-/low." (PMID 26355461, 2015).